MUC4 (mucin 4, cell surface associated)
Diseases named in the same sentence as MUC4 in open-access papers (continued):
Sharing a sentence is not in itself a finding about the gene and the disease.
tumor (continued). "MUC4 and AHNAK2 were the most frequent differential genes in invasive disease compared with that in in situ; they may play the role of promoting tumor invasion." (PMID 36091120, 2022). "Because of the decreased molecular weight of VHH, only approximately 50% of HER2 is masked by MUC4 to 99mTc-MIRC208, which may lead to confusing results when the tumor expresses an extremely high HER2 level." (PMID 35910795, 2022). "In the present study, we observed that Muc13 was upregulated in the absence of Muc4, suggesting its tumor-promoting role in CRC." (PMID 35255004, 2022). "MUC4/HER2 is a pro-oncogenic complex involved in cancer cell tumorigenic properties and in activation of different oncogenic signaling pathways leading to tumor progression in many epithelial cancers (lung, esophagus, colon, breast, and pancreas)." (PMID 34830899, 2021). "Aggressive low-grade peripheral sheath tumor cells show a curly tapered nucleus and cytological atypia and are positive for S100 and SOX10 and negative for MUC4; they show loss of expression for H3K27me." (PMID 33526082, 2021). "MUC4, a large membrane-anchored glycoprotein, can facilitate tumor angiogenesis and increase tumor MVD in PC by activating Notch3 signaling and downstream pro-angiogenic genes, including VEGF-A and ANG-2." (PMID 34195229, 2021). "By immunohistochemistry, tumor cells demonstrated strong nuclear cyclin D1 expression and multifocal smooth muscle actin staining but were negative for MUC4, ERG, CD34, S-100 protein, desmin, STAT6, CD45, MDM2, CDK4, ALK, and ROS1." (PMID 32461620, 2020). "Of note, the only patient with a diagnosis of small‐cell lung cancer and RNA data (Patient 4) had RNA profiles from two tumor sites that were similar to each other and distinct from the other NSCLC tumors with higher levels of several mucins and surfactant proteins (MUC4, MUC5B, MUC6, SFTPB)." (PMID 31747139, 2020). "Because pro-inflammatory cytokines have been previously shown to stimulate expression of membrane-bound mucins such as MUC1, MUC4, and MUC16 in tumor cells, we hypothesized that ascites could enhance MUC16 expression in HPMCs." (PMID 31039761, 2019). "Six genes were found to be altered in two tumours: MYO1A, DNAH11, SH2D5, ATM, MUC4 and ROS1." (PMID 29665859, 2018). "MUC4, MUC16 and MUC20 mRNA expression was evaluated in datasets to analyze whether the mRNA level differed between normal and tumor tissues." (PMID 30236127, 2018). "A reduced expression of MUC4 was observed in LUSC tumors, especially in advanced tumor stages." (PMID 29484121, 2018). "Furthermore, subgroup analysis stratified by nationality, cancer type, adjuvant therapy, sample size, methods, cut-off value, MUC subtype, tumor location, antibody for MUC1 and antibody for MUC4 were performed respectively." (PMID 29221212, 2017). "Radioactivity accumulation in non-tumor as well as in the MUC4-negative SKBr3 tumor was not significantly altered by long term NAC exposure." (PMID 28915583, 2017). "DF3 for MUC1 may be a more tumor-specific antibody in immunohistochemistry than others (i.e. VU4H5) in HNC especially for paraffin-embedded tissues, as the same to 8G7 for MUC4." (PMID 29221212, 2017). "In the MUC4-overexpressing trastuzumab resistant JIMT1 tumors, tumor metabolic changes were observed exclusively in the treatment arm combining trastuzumab and NAC with a significantly lower %ΔSUVmax (NT = 12.6 ± 7.8 % vs CT = 78.6 ± 10.6, NS = 62.1 ± 12.1 and CS = 75.1 ± 15.5; all p < 0.01)." (PMID 28915583, 2017). "Our results showed that as same as tumor location, tumor differentiation, TNM staging, serum level of CA19-9, serum level of CA50, serum level of CEA and MUC4 mRNA expression status, MUC4/Y mRNA expression level was also significant predictor of survival in univariate analysis." (PMID 25367394, 2014). "The results indicate that the tumour volume was significantly lower in xenografted mice with M4-2-1 or M4-2-10 clones at day 22 in which absence of MUC4 was confirmed by IHC." (PMID 22393391, 2012).
tumor (continued). "Whereas CK20 was non-significant, MUC1 expression in ≥40% of tumour cells (P = 0.038) and MUC4 expression in any tumour cell (P = 0.029) each significantly predicted a poor prognosis." (PMID 19236510, 2009). "In BTC, recent studies from east Asia suggest that MUC4, as well as MUC5AC, may be suitable candidate tumour markers." (PMID 18475301, 2008). "MUC4 expression pattern did not significantly correlate with the stage of tumour, both individually (P=0.16) or in groups, that is, I/II (early stage) and III/IV (late stage) (P=0.21)." (PMID 18781152, 2008). "The metastasised LN tumours showed morphology and MUC4 staining similar to that observed in the OT tumours (data not shown)." (PMID 14760381, 2004). "The positive staining in the OT tumour section was specifically blocked by pre-incubation of the MUC4-antiserum with the tandem repeat peptide (data not shown)." (PMID 14760381, 2004). "Total RNA isolated from the tumour cell line (CD18/HPAF), tumour tissues, and normal human pancreas was fractionated on agarose gel electrophoresis, Northern blotted, and probed with a MUC4 tandem repeat cDNA probe." (PMID 14760381, 2004). "Among eight mucin genes analysed, MUC4 was the only gene that showed high levels of expression in OT tumours, with no detectable expression in the normal pancreas or SC tumours." (PMID 14760381, 2004). "Sometimes, a very low level of TGFβ2 was detected in SC tumours (two out of the six) without expression of MUC4 (data not shown)." (PMID 14760381, 2004). "Another factor relating to better therapy response in HPV(+) tumors could be that HPV(−) exosomes are enriched in tumor-promoting and immunosuppressive proteins such as MUC-1, HLA-DRA, MUC-4, and MUC-16, which give protection to tumor cells against NK cell-mediated lysis." (PMID 41154440, 2025). "MUC4’s juxtamembrane EGF-like domains are responsible for preventing EGFR ubiquitination and degradation upon ligand stimulation, which allows for persistent activation of downstream signaling pathways essential for tumor development, such as the ERK and PI3K/Akt pathways." (PMID 40655139, 2025). "Similarly, altered expression of MUC4 and MUC6 has been reported in CRC and may influence tumor aggressiveness and patient outcomes." (PMID 39682117, 2024). "Besides MUC2 and MUC5AC, other mucins, such as MUC1, MUC4, and MUC6, may also be dysregulated in CRC and contribute to tumor progression." (PMID 39682117, 2024). "In the present study, we first analyzed the tumor and adjacent non-tumor tissues of the GC patient cohorts and the biopsy tissues of the FD patients to measure the relative mRNA expression of gastric (MUC1, MUC5AC, MUC6) and intestinal (MUC2, MUC4, MUC13) mucins." (PMID 37085819, 2023). "This suggested that MUC4 protein was absent within tumor cells." (PMID 38156143, 2023). "Thus, if we want to use 99mTc-MIRC208 to determine whether MUC4 masks the Traz epitope, we must know the HER2 expression level in tumor in advance." (PMID 35910795, 2022). "99mTc-MIRC213 could be used to select HER2-positive patients and noninvasively quantify the tumor HER2 expression levels without the interference from MUC4." (PMID 35910795, 2022). "MUC4 knockdown in MDA-MB-231 cells reduced their tumorigenic and metastatic properties, suggesting MUC4 may represent a gene that contributes to ALDH1A3/RA-mediated tumor growth and metastasis of MDA-MB-231 cells." (PMID 31590252, 2019). "This may be because MUC4 is expressed only in neoplasms with poor outcome, as most lung tissue does not express MUC4." (PMID 28680536, 2017). "In the present study, we hypothesized that MUC4-related resistance to trastuzumab can be overcome through the use of a mucolytic drug, by improving the accessibility of the drug to HER2 and hence achieve a better anti-tumor effect." (PMID 28915583, 2017). "However, on immunohistochemical analysis, the tumor was unexpectedly positive for MUC4, but negative for desmin, S100, smooth muscle actin, CD34, and CD117." (PMID 27247823, 2016).
tumor (continued). "From these results, we hypothesize that MUC4 inhibition induces expression of TGF-β1 at the mRNA level to create a loop of regulation (feedback) that would result in up-regulation of ErbB2 or MUC4 and promote tumour cell proliferation." (PMID 22393391, 2012). "The observation suggests a role of serum factors in regulating the MUC4 expression, or there may be a clonal expansion of a non-MUC4-expressing cell type in the SC tumours." (PMID 14760381, 2004). "MUC4 was negative in case 1, but it displayed a peculiar pattern of immunostaining in case 2, being positive at the membranes lining the lumina of the small cystic or cribriform formations, as well as a focal membranous positivity in the solid areas of the tumor." (PMID 37415052, 2023). "However, these tumors, while comparable in size to the previously obtained control tumors (0.75 g), were still incapable of distant metastasis, suggesting that the differences in the metastatic potential of control and MUC4 knockdown cells is independent of the size of the primary tumor." (PMID 23408941, 2013). "We chose three tumor cell lines: Two with documented expression of MUC4 (HPAF-II and Capan-1) and one that was known not to express MUC4 (PANC-1)." (PMID 40649822, 2025). "Apical membranes were not visible in 7% of tumours analysed for MUC1 and in 6% of tumours analysed for MUC4." (PMID 39966658, 2025). "The tumor cells expressed CD99, synaptophysin, CD56, MUC4, and EMA (focal), but not AE1/AE3, S100, smooth muscle actin, desmin, CD34, chromogranin A, GFAP, NKX2-2, PAX7, and INSM1." (PMID 39249507, 2024). "In a recent study, mesothelin, mucin 4 (MUC4), annexin A10 (ANXA10), and glypican 1 (GPC-1) were observed to be selectively expressed in the tumor when compared to non-neoplastic pancreatic ducts and acini." (PMID 39062863, 2024). "IHC analyses revealed that the tumor cells were positive for EMA and CD34 and negative for claudin-1, GLUT1, S100 protein, MUC4, STAT6, SMA, HMB45 and P16." (PMID 34592995, 2021). "5-Aza-CdR interestingly decreased levels of genes that promote tumor progression, such as CCND1, MKI67, BIRC5, and BCL2, but failed to decrease MUC4 and NOTCH1." (PMID 32182826, 2020). "The clinical parameters including age, gender, tumor subtype, T value, N value, tumor stage and grade are not significantly correlated with IL-17RB, MUC1, or MUC4 expression." (PMID 33082357, 2020). "MUC4 was differentially expressed in SSA/P and TA versus benign lesions (HP) however; it did not appear as a significant contributor in the combinatorial panels of markers that discriminated these polyp subtypes." (PMID 27705923, 2017). "In tumor cells accustomed to long-term EMT, MUC4 freely binds with molecules that normally do not appear on the non-apical surface, which contributes to a sustained state of reduced cell polarity." (PMID 27829225, 2017). "On immunohistochemical examination, the tumor cells were negative for desmin, S100, smooth muscle actin, CD34, and CD117 and were positive for MUC4." (PMID 27247823, 2016). "Decreased proliferation in cells lacking MUC4 is most likely due to the alteration of the JNK pathway since it is known that this pathway promotes proliferation and decreased apoptosis in a tumour context, two alterations that we found in MUC4-deficient cells." (PMID 22393391, 2012). "Essentially all the tumor cells demonstrated strong cytoplasmic MUC1 staining, but were negative for MUC2, MUC4, MUC5AC and MUC6." (PMID 20550696, 2010). "Moreover, by immunohistochemistry (IHC), the tumor showed diffuse reactivity for vascular markers, including ERG, CD31, CD34, and D2-40, as well as for TFE3, while being negative for MUC4, CAMTA1, smooth-muscle actin, desmin, S100 and keratins." (PMID 40879254, 2025).
tumor (continued). "Regarding the intestinal mucins, a significant increase in MUC13 mRNA expression was seen in the paired tumor tissues compared to the adjacent non-tumor and FD tissues whereas no significant alterations in expression were seen for MUC2 and MUC4 mRNA among the different sample types." (PMID 37085819, 2023). "The SPECT/CT studies with 99mTc-MIRC208 and 99mTc-MIRC213 clearly showed that the MUC4-negative and trastuzumab-sensitive 7HER2 and NCI-N87 tumors had very similar tumor uptake with the SUV208/SUV213 (2 h) ratios of 1.11 ± 0.17 in 7HER2 and 1.25 ± 0.22 in NCI-N87." (PMID 35910795, 2022). "This tumor is positive for ASMA and beta-catenin and negative for MUC4." (PMID 33526082, 2021). "Tumor cells are positive for S100, SOX10, and CD34 and negative for MUC4." (PMID 33526082, 2021). "The tumor cells are immunostain positive for INSM1, SOX9, CD99 and S100, but negative for MUC4." (PMID 32164724, 2020). "The tumor in our case was negative for MUC2, MUC4, MUC5AC and MUC6." (PMID 20550696, 2010). "All tumours displayed a high and constant expression of MUC2 and no expression of MUC4 mRNA." (PMID 14760390, 2004). "Also, the two tumor lines used in the Jaiswal study (SW1990 and CD18/HPAF) were different from ones used in our present work (Capan-1, HPAF-II, and BxPC3) and no control MUC4-negative cell line was analyzed." (PMID 40649822, 2025). "Additionally, the tumor was negative for most immunohistochemical markers (CKAE1/AE3, p63, CD23, CD21, MUC4, NUT, CDK4, Pan-TRK, STAT6, SS18, MDM2, Desmin, S100, ERG, TLE1, Fli) and showed only weak and most probably unspecific expression of CD99, CD56, and CD34." (PMID 39519042, 2024). "(Immunohistochemical stains showed that the tumor cells were positive for desmin and TFE3, while negative for pancytokeratin, CAM5.2, EMA, chromogranin, synaptophysin, NSE, CD45, SMA, HHF35, myogenin, CD117, DOG1, MUC4, S100, SOX10, HMB45, Melan-A, CD31, ERG, TLE1, STAT6, and Cathepsin-K)." (PMID 35001360, 2022). "Similarly, MUC4 but not MUC5AC was found to be overexpressed in the majority of early PanINs in a human pancreatic specimen, which predominantly consisted of small‐sized PanINs suggestive of early‐stage lesions, as well as in stage I/II of PDAC tumor specimens." (PMID 37964407, 2023).
cancer (207 papers, 2004 to 2025). A tumor composed of atypical neoplastic, often pleomorphic cells that invade other tissues. "The ExCy and Fujifilm’s mRNA transcripts in the Disease pathway were revealed by TCGA’s Cancer Gene Consensus analysis to be more likely mutated: MUC4, CDK4, and CD79A, ARAF, respectively." (PMID 40598203, 2025). "Analysis of cancer-related mutations excluded hypermutated genes such as MUC4 and revealed 18–65 mutations per model, which was largely consistent across samples." (PMID 40605119, 2025). "MUC4 (mucin 4, cell surface-associated) is a transmembrane glycoprotein that is implicated in the pathogenesis of various human cancers." (PMID 39548061, 2024). "MUC4, mutated in 11.36% and 10% of our rNEN-S and rNEN-L subjects, has also been revealed to be aberrantly expressed in a variety of epithelial carcinomas and can serve as a clinical tool for cancer diagnosis and prognosis." (PMID 39548061, 2024). "WES, followed by calculation of genomic status, reveals that alterations in non‐cancer‐associated genes such as MUC4 are associated with RFS of stage I NSCLC." (PMID 37712717, 2023). "Particularly MUC4 overexpression has been associated with various types of cancer, which underscores the need for a rigorous evaluation of eventually infection-protective pathways for severe adverse effects." (PMID 36554876, 2022). "In our research, comparing invasive to in situ, half of the paired cases showed MUC4 mutation, hence we supposed it as a biomarker for cancer progression risk detection and intervention treatment." (PMID 36091120, 2022). "The evaluated expression of the rs2641726 C allele of MUC4 was significantly concerned with cancer incidence by providing a binding site to attenuate its interaction with miR-581." (PMID 36142830, 2022). "MUC4, a high molecular weight glycoprotein, is found to be associated with enhanced cancer cell invasion and EMT in several types of cancers." (PMID 35912006, 2022). "We further explored genomic and epigenetic alterations of MUC4, its association with proliferation and metastasis, and the correlation with immune infiltration in different cancers." (PMID 34336844, 2021). "This strategy will represent a new efficient alternative to treat cancers associated with MUC4/HER2 overexpression and HER2-targeted therapy failure as a new adapted treatment to patients." (PMID 34830899, 2021). "In malignant tumors of the pancreas, ovary, and breast, mutation/overexpression of MUC4 has been fully demonstrated, and the overexpression of MUC4 is involved in trastuzumab resistance." (PMID 33968045, 2021). "MUC4 is an explicit marker of epithelial tumors, and its expression is linked to the degree of differentiation in various cancers." (PMID 34604242, 2021). "And the MUC4 variants were found in higher frequency in The Cancer Genome Atlas Study (TCGA) germline samples of patients with multiple cancer types." (PMID 32701958, 2020). "In the same manner as MUC1, MUC4 overexpression in cancer promotes IPF-linked processes including myofibroblast transition, proliferation, migration and metastasis." (PMID 31514468, 2019). "This epitope represents a novel immunogen to potentially develop diagnostic antibodies or immunotherapies against various MUC4-positive cancers." (PMID 30952968, 2019). "MUC4 is typically hypomethylated in cancers, and its expression is associated with more aggressive cancer." (PMID 31590252, 2019). "Experimental evidence has demonstrated that MUC4 overexpression in cancer cells is associated with increased expression of EMT-related transcription factors such as TWIST, ZEB1 and SNAIL." (PMID 31514468, 2019). "MUC4 is associated with changes in ErbB2 expression, apoptosis, proliferation, differentiation, and some cancers." (PMID 31744086, 2019).